ENSG00000269476 (novel transcript)
Gene: Protein-coding gene on chromosome 19 (57,876,765 to 57,916,591, reverse strand). Ensembl gene ENSG00000269476.
Genetic constraint (gnomAD): Missense variants: 15 observed, 12.36 expected, observed/expected ratio (o/e) 1.21, 90% interval 0.81 to 1.79. Synonymous variants: 3 observed, 6.29 expected, observed/expected ratio (o/e) 0.48, 90% interval 0.22 to 1.23.